GCKR (glucokinase regulator)
Diseases named in the same sentence as GCKR in open-access papers (continued):
Sharing a sentence is not in itself a finding about the gene and the disease.
tumor (1 paper, 2025). "In CHOL, GCKR was associated with various signaling pathways, indicating a potentially significant role in tumor progression." (PMID 41235343, 2025). "Of particular note, missense mutations were the most common type of SNV identified in GCKR, hinting at possible functional alterations in the GCKR protein that may contribute to tumor progression." (PMID 41235343, 2025). "Furthermore, in KIPAN, KIRC, and PAAD, GCKR expression was positively associated with pathological grade, indicating a potential role in tumor progression." (PMID 41235343, 2025). "Overall, this research aims to elucidate the functional mechanisms of GCKR in the “immune-cold” state and provide a theoretical basis for the development of novel tumor immunotherapy targets." (PMID 41235343, 2025). "By shaping tumor metabolism and immune infiltration, GCKR emerges as both a biomarker and a potential therapeutic guide." (PMID 41235343, 2025). "We next explored the relationship between GCKR expression and clinical parameters such as tumor stage, patient age, and sex." (PMID 41235343, 2025). "GCKR, a key regulator of glucose metabolism, is found to be downregulated in most tumor tissues, with particularly marked differences in BRCA and CHOL." (PMID 41235343, 2025). "To investigate the differential expression of GCKR between tumor and normal tissues, we analyzed unpaired samples from the TCGA and TCGA–GTEx databases." (PMID 41235343, 2025). "Given the crucial role of the immune microenvironment in tumor development, we analyzed the correlation between GCKR and immune-related genes and cells." (PMID 41235343, 2025). "This variation suggests that GCKR may play a dual regulatory role depending on the tumor context, potentially contributing to the modulation of complex metabolic–immune networks." (PMID 41235343, 2025). "This suggests that GCKR may influence immune cell recruitment, activation, and function, thereby playing a role in tumor development." (PMID 41235343, 2025). "This may imply a potential role for GCKR in CAF function or in CAF-mediated remodeling of the tumor microenvironment." (PMID 41235343, 2025). "Given the strong link between tumor grade, staging, and prognosis, GCKR may serve as a useful marker for early diagnosis." (PMID 41235343, 2025). "Our analysis reveals that GCKR expression correlates with tumor pathological grade." (PMID 41235343, 2025). "Nevertheless, whether GCKR contributes to regulating the tumor immune microenvironment or influences responses to immunotherapy remains unresolved." (PMID 41235343, 2025). "GCKR was found to correlate positively with several gene sets involved in tumor functional states." (PMID 41235343, 2025). "This implies that GCKR may influence tumor progression by regulating these pathways." (PMID 41235343, 2025). "Importantly, single-cell and spatial transcriptomic analyses revealed that GCKR-positive subpopulations are enriched for mitochondrial and metabolic pathways, and their localization within tumor niches provides a mechanistic link between metabolic heterogeneity and immune exclusion." (PMID 41235343, 2025). "For example, in CHOL, GCKR showed strong positive correlations with JNK2 and P62LCKLIGAND, suggesting that GCKR might influence tumor survival and apoptosis by modulating these pathways—findings consistent with prior reports." (PMID 41235343, 2025).
GCKR also shares sentences with these, for which no sentence is quoted: Glucose intolerance (4 papers); rheumatoid arthritis (3); celiac disease (2); central obesity (2); kidney damage (2); kidney disease (2); mental disorder (2); non-alcoholic fatty liver (2); age-related macular degeneration (1); aging (1); alcoholic cirrhosis (1); alcoholism (1); Aldob deficiency (1); Alstrom syndrome (1); asthma (1); cholangiocarcinoma (1); cocaine dependence (1); coronary atherosclerosis (1); dyslipidaemia (1); endocrine disorders (1); essential hypertension (1); glioma (1); Hyperinsulinemia (1); hyperinsulinemic hypoglycemia (1); hyperlipoproteinemia type I (1); Impaired glucose tolerance (1); insulinoma (1); ischaemic heart disease (1); kidney transplant (1); nephrotic syndrome (1).
A further 14 diseases each share a sentence with GCKR in 1 paper.